TMEM117 (transmembrane protein 117)
Description:
Involved in endoplasmic reticulum (ER) stress-induced cell death pathway.
Synonyms: DKFZp434K2435
Tractability: Antibody: UniProt places it where antibodies can reach, with high confidence; its Gene Ontology location is reachable by antibodies, with high confidence; UniProt predicts a signal peptide or a membrane-spanning region.
Gene: Protein-coding gene on chromosome 12 (43,835,967 to 44,389,762, forward strand). Ensembl gene ENSG00000139173.
Subcellular location: Cell membrane
Gene Ontology:
Biological process: intrinsic apoptotic signaling pathway in response to endoplasmic reticulum stress
Cellular component: endoplasmic reticulum; plasma membrane
Genetic constraint (gnomAD): Loss-of-function variants: 20 observed, 43.38 expected, observed/expected ratio (o/e) 0.46, 90% interval 0.32 to 0.67. The upper end of that interval is the gene's LOEUF score, 0.67, which puts it in group 2 of 6, group 1 being the genes least tolerant of losing a copy. Missense variants: 486 observed, 586.24 expected, observed/expected ratio (o/e) 0.83, 90% interval 0.77 to 0.89. Synonymous variants: 194 observed, 199.42 expected, observed/expected ratio (o/e) 0.97, 90% interval 0.87 to 1.1.
Homologues: Orthologues: chimpanzee TMEM117 (100% identical), macaque TMEM117 (99% identical), pig TMEM117 (98% identical), dog TMEM117 (98% identical), guinea pig TMEM117 (97% identical), mouse Tmem117 (96% identical), rat Tmem117 (96% identical), rabbit TMEM117 (83% identical), tropical clawed frog tmem117 (76% identical), zebrafish tmem117 (50% identical).
Diseases named in the same sentence as TMEM117 in open-access papers:
TMEM117 is named in the same sentence as 13 diseases in open-access papers, as found by Europe PMC text mining. Sharing a sentence is not in itself a finding about the gene and the disease. The quoted sentences say what the papers report.
glioma (2 papers, 2020 to 2023). A benign or malignant brain and spinal cord tumor that arises from glial cells (astrocytes, oligodendrocytes, ependymal cells). "Bioinformatic analysis revealed an association between TMEM117 downregulation and pancreatic cancer tumorigenesis and metastasis, trans-differentiation to mesenchymal cells in breast cancer, phenotypic change of normal cells of gliomas, and development of malignant lymphoblastic leukemia." (PMID 32206039, 2020). "Previous studies indicated that TMEM117 was downregulated in tumors and its downregulation was suppressed during the phenotypic change to normal cells in gliomas." (PMID 37488300, 2023).
Malignant lymphoblastic leukemia (2 papers, 2020 to 2023). "Malignant lymphoblastic leukemia has shown low levels of expressed TMEM117." (PMID 37488300, 2023).
cardiac hypertrophy (1 paper, 2023). "The present study provides evidence that upregulation of TMEM117 contributes to the development of cardiac hypertrophy and TMEM117 deficiency attenuates cardiac hypertrophy, likely through ameliorating mitochondrial injury and oxidative stress." (PMID 37488300, 2023). "We found that TMEM117 was upregulated in hypertrophic hearts and cardiomyocytes and TMEM117 deficiency attenuated Ang-II-induced cardiac hypertrophy in vivo." (PMID 37488300, 2023). "To confirm the injury-mitigation roles of oxidative stress and TMEM117 deficiency, we investigated effects of TMEM117 overexpression on oxidative stress in cardiac hypertrophy." (PMID 37488300, 2023). "Taken together, this demonstrates that deficiency of TMEM117 protects against Ang-II-induced cardiac hypertrophy." (PMID 37488300, 2023). "Third, the cardioprotective effects of TMEM117 deficiency in cardiac hypertrophy were associated with suppressed oxidative stress, ERS and improved mitochondrial function, which were abolished by TMEM117 supplementation." (PMID 37488300, 2023). "Taken together, these findings suggest that the deficiency of TMEM117 protects against cardiac hypertrophy through ameliorating mitochondrial injury and oxidative stress." (PMID 37488300, 2023). "With genetic method, we found that TMEM117 deficiency attenuated Ang-II-induced cardiac hypertrophy both in vivo and in vitro." (PMID 37488300, 2023). "The present study investigated the effects of TMEM117 deficiency and upregulation on the development of Ang-II-induced cardiac hypertrophy and underlying mechanism." (PMID 37488300, 2023). "To investigate whether TMEM117 is associated cardiac hypertrophy, we first detected the expression of TMEM117 in the hypertrophic hearts and isolated NMVMs." (PMID 37488300, 2023). "The mechanism underlying the upregulation of TMEM117 in cardiac hypertrophy are still unknown." (PMID 37488300, 2023). "Second, loss-of-function and gain-of-function experiments demonstrated that TMEM117 knockdown attenuated, while TMEM117 overexpression aggravated, cardiac hypertrophy induced by Ang-II both in vivo and in vitro." (PMID 37488300, 2023). "We have constructed TMEM117 transgenic mice in our lab and in the future, we certainly will conduct more research and exploration on the role of TMEM117 in the process of cardiac hypertrophy." (PMID 37488300, 2023). "Cardiac TMEM117 overexpression deteriorated Ang-II-induced cardiac hypertrophy, as indicated by enlarged cardiomyocytes area, increased interstitial fibrosis and collagen deposition, as well as elevated HW/BW and HW/TL ratios." (PMID 37488300, 2023). "Taken together, these data indicated that cardiac TMEM117 overexpression aggravated Ang-II-induced cardiac hypertrophy." (PMID 37488300, 2023). "Cardiac-specific TMEM117-knockout and control mice were subjected to cardiac hypertrophy induced by Ang-II infusion." (PMID 37488300, 2023). "Collectively, these results supported the conclusion that reduced TMEM117 alleviated abnormal mitochondrial morphology and function, inhibiting oxidative stress, and ameliorating pathological cardiac hypertrophy." (PMID 37488300, 2023). "We further examined the relationship between TMEM117 and oxidative stress in Ang-II-induced cardiac hypertrophy." (PMID 37488300, 2023). "We also found that knockout of TMEM117 protected mitochondrial morphology and function in Ang-II-induced cardiac hypertrophy." (PMID 37488300, 2023). "In contrast, TMEM117 overexpression aggravated abnormal mitochondrial morphology and mitochondrial dysfunction induced by cardiac hypertrophy." (PMID 37488300, 2023). "To clarify the functional role of TMEM117 in cardiomyocytes during Ang-II-induced cardiac hypertrophy, we generated cardiomyocyte-specific conditional TMEM117-knockout (TMEM117 cKO) mice." (PMID 37488300, 2023).
cardiac hypertrophy (continued). "Since mitochondrial dysfunction and oxidative stress are all closely involved with cardiac hypertrophy, we speculate that there might be a chance TMEM117 participates in the process of Ang-II-induced cardiac hypertrophy." (PMID 37488300, 2023). "Collectively, these findings indicated that TMEM117 might take part in the Ang-II-induced cardiac hypertrophy." (PMID 37488300, 2023). "Taken together, these findings suggest that upregulation of TMEM117 contributes to the development of cardiac hypertrophy and the downregulation of TMEM117 may be a new therapeutic strategy for the prevention and treatment of cardiac hypertrophy." (PMID 37488300, 2023). "In contrast, the overexpression of TMEM117 aggravated cardiac hypertrophy." (PMID 37488300, 2023). "Thus, the in vivo and in vitro data indicated that antioxidative effect of TMEM117 cKO in Ang-II-induced cardiac hypertrophy." (PMID 37488300, 2023). "In summary, we demonstrate a novel role of TMEM117 in cardiac hypertrophy." (PMID 37488300, 2023). "Conversely, overexpression of TMEM117 exacerbated cardiac hypertrophy and dysfunction." (PMID 37488300, 2023). "Thus, we hypothesized that TMEM117 might serve as the major molecule in the development of myocardial hypertrophy." (PMID 37488300, 2023). "Therefore, we next focused whether TMEM117 regulates cardiac hypertrophy by modulating ERS-mediated ROS generation." (PMID 37488300, 2023). "We speculated that TMEM117 may mediate direct Ang-II-induced cardiac hypertrophy rather than hypertension-induced hypertrophy." (PMID 37488300, 2023).
developmental delay (1 paper, 2018). "So far no paper published has reported that TWF1 or TMEM117 is connected with developmental delay." (PMID 30155906, 2018).
Hypertension (1 paper, 2023). The presence of chronic increased pressure in the systemic arterial system. "Specially, blood pressure was indistinguishable between TMEM117 knockdown and control mice, suggesting that TMEM117 do not affect Ang-II-induced hypertension." (PMID 37488300, 2023). "Blood pressure was indistinguishable between TMEM117M cKO and control mice, suggesting that TMEM117 do not affect Ang-II-induced hypertension." (PMID 37488300, 2023).
Hypoglycemia (1 paper, 2026). A decreased concentration of glucose in the blood. "TMEM117, a gene involved in response to ER stress and hypoglycemia was also upregulated, suggesting that control synaptic OLs may be enhancing glucose uptake via glutamate signaling." (PMID 41283828, 2026).
rubella (1 paper, 2023). A viral infection caused by the rubella virus. "Similarly, in transformed fibroblast cells, we found PPP2R1B (padjusted = 0.022), C11orf1 (padjusted = 0.029), DLAT (padjusted = 0.045), and TMEM117 (padjusted = 0.046) as rubella-related genes." (PMID 37020999, 2023). "In rubella, including five in whole blood (JAGN1, RRP12, RP11-452K12.7, CASP7, and AP3S2), four in the lung tissue (IL17RC, FAM86HP, AMACR, and RRP12), and four in the transformed fibroblast cells (PPP2R1B, C11orf1, DLAT, and TMEM117)." (PMID 37020999, 2023).
cancer (3 papers, 2020 to 2023). A tumor composed of atypical neoplastic, often pleomorphic cells that invade other tissues. "TMEM117 is expressed in a variety of normal tissues and organs, and it is mostly involved in the physiological and pathological processes of cancers." (PMID 37488300, 2023). "Although the three genes (GRID2IP, TMEM117, HLA-DP) are involved in the progression of cancers, their role in GC is unclear." (PMID 32206039, 2020). "These research results indicate that TMEM117 plays an important role in the development of cancer." (PMID 37488300, 2023). "In addition, the Kaplan–Meier analysis was applied to study the relationship between the expression level of TMEM117 and the prognosis of cancer patients." (PMID 34804929, 2021). "However, experiment data are insufficient to support a role of TMEM117 in cancers, further research is required to identify the tumorigenic role of TMEM117 protein levels in cancer." (PMID 32206039, 2020).
cardiovascular disease (1 paper, 2023). "Until now, the precise role of TMEM117 in cardiovascular disease is not known." (PMID 37488300, 2023). "However, the roles of TMEM117 in cardiovascular diseases have not been elucidated." (PMID 37488300, 2023).
tumour (1 paper, 2019). "Eighteen mutated genes were positively selected in the relapse tumour which were already present in the primary tumour (diagnosis) at low VAF (<1%) and 2 genes were relapse-specific (ETV6 and TMEM117)." (PMID 31540260, 2019).
TMEM117 also shares sentences with these, for which no sentence is quoted: breast carcinoma (1 paper); gestational diabetes (1); pancreatic cancer (1).